APOE (apolipoprotein E)
Diseases named in the same sentence as APOE in open-access papers (continued):
Sharing a sentence is not in itself a finding about the gene and the disease.
atherosclerosis (continued). "Recent studies in apoE-/- mice have demonstrated a reduction in atherosclerosis development using an immunodeficiency strategy, low dose of the phytochemical tetrahydrocannabinol, antioxidant N-Acetylcysteine, PARP inhibition or mononuclear cell therapy." (PMID 22330242, 2012). "To further elucidate the impact of ARE on atherosclerosis, we investigated its effects in apoE−/− mice fed on an atherogenic diet." (PMID 22536886, 2012). "BxH-ApoE consisted of an F2 population derived from a backcross of mice highly susceptible to atherosclerosis (C57BL/6J ApoE−/−) and highly resistant (C3H/HeJ ApoE−/−)." (PMID 22916037, 2012). "In conclusion, these data indicate that H2S hampers the progression of atherosclerosis in fat-fed apoE−/− mice and downregulates CX3CR1 and CX3CL1 expression on macrophages and in lesion plaques." (PMID 22815945, 2012). "Macrophage NO production (most actively from inducible nitric oxide synthase [iNOS]) is most likely harmful, because iNOS knockout attenuates atherosclerosis in apoE−/− mice." (PMID 22934038, 2012). "ApoE−/− mice have been widely used as an animal model of atherosclerosis and the murine carotid plaque induced by high-fat diet feeding and paravascular collar placement has been recognized as the most reproducible site for studies of advanced lesions." (PMID 22428064, 2012). "In-vivo in the same animal model, ApoE knock-out mice, catechin, anthocyanin or curcumin significantly reduced atherosclerosis lesion development via a lower monocyte infiltration." (PMID 22253797, 2012). "Development of atherosclerosis was associated with significant increase of FDG-6-P amount in the extracts of normal chow-fed ApoE KO mice and dramatic accumulation in aortas of ApoE KO mice with the diet-induced increase in the plaque coverage." (PMID 23209718, 2012). "The apoE-/- model has been used widely due to the rapid development of atherosclerosis, despite considerable limitations." (PMID 22762542, 2012). "Adoptive transfer studies have shown that in Apoe−/− mice, even a 10% restoration of plasma apoE levels by macrophages is sufficient to normalize plasma cholesterol levels and prevent the formation of atherosclerosis." (PMID 22606237, 2012). "We next assessed the contribution of macrophage-derived apoE expression levels on atherosclerosis in Apoeh/h and Apoeh/hLysM-Cre mice fed a HCD." (PMID 22606237, 2012). "Our data reveal that low levels of macrophage-derived apoE can effectively control the progression of advanced atherosclerosis in which cells other than foam cells accumulate." (PMID 22606237, 2012). "Our models offered several advantages over existing models that previously served to address the role of macrophage-derived apoE in hyperlipidemia and atherosclerosis." (PMID 22606237, 2012). "As vascular calcification is considered an independent risk factor for plaque instability, we here investigated the effect of VKA on coronary calcification in patients and on calcification of atherosclerotic plaques in the ApoE−/− model of atherosclerosis." (PMID 22952653, 2012). "In apoE-/- mice, Ang II also contributes to increased NADPH-dependent vascular •O2- production and is implicated in the pathogenesis of atherosclerosis and endothelial dysfunction in this model." (PMID 22082357, 2011). "Within macrophages, LRP1 has been shown to reduce the extent of atherosclerosis in LDL receptor/apoE double knockout mice and in LDL receptor knockout mice." (PMID 22174911, 2011). "To avoid the influence of the cholate diet, we constructed BALB.apoE-/- mice that developed spontaneous hyperlipidemia and atherosclerosis on a low fat chow diet." (PMID 22204493, 2011).
atherosclerosis (continued). "Similar findings have been observed in ApoE-/- mice exposed by inhalation to concentrated ambient air particles where the progression of atherosclerosis was largest in mice on a high-fat diet." (PMID 22074227, 2011). "In the present study we observed that MNCs have atheroprotective properties in an apoE KO murine model of atherosclerosis, even under conditions of high total cholesterol in the plasma." (PMID 21896159, 2011). "In support of these findings, a recent study showed that in apoE-/- mice, atherosclerosis was reduced following ovariectomy and was aggravated following treatment with 17-β-estradiol at doses that were similar to physiological levels of the hormone." (PMID 22082357, 2011). "The key role of IFNγ has been confirmed in experimental atherosclerosis whereby ApoE-/- IFNγ receptor-/- mice displayed a substantial reduction in lesion size compared to ApoE-/-." (PMID 21526997, 2011). "Treatment with TO901317 prevented atherosclerosis in various mouse models, and increased apoE-rich HDL particles in C57BL6 mice." (PMID 21819577, 2011). "The effect of ranolazine was analyzed in two experimental models of heart failure, i.e. 10 month-old B6 mice with 6 months of chronic pressure overload and 18 month-old ApoE-/- mice with advanced atherosclerosis." (PMID 21711241, 2011). "It has been shown that ITGAX deficiency reduced the firm arrest of monocytes on vascular cells, monocyte/macrophage accumulation in intimae and consequently, reduced atherosclerosis development in apoE−/− mice fed a high-fat diet." (PMID 22110589, 2011). "Apolipoprotein E (apoE) is a major protein of the lipoprotein transport system that plays critical role in the protection from atherosclerosis and dyslipidemia." (PMID 22069485, 2011). "Compared to B6.apoE-/- mice, BALB.apoE-/- mice are highly resistant to atherosclerosis, developing much smaller lesions." (PMID 22204493, 2011). "Combined inhibition of CCL2, CCR5 and CX3CR1 in ApoE-/- mice results in a 90% reduction in atherosclerosis, which is related to progressive monocytopaenia." (PMID 21526997, 2011). "Despite a growing body of evidence suggesting that gender influences atherosclerosis in apoE-/- mice, few studies have investigated the differences in endothelial function between males and females." (PMID 22082357, 2011). "Consistent with the human studies, partial ablation of Irs2 in apoE−/− mice also reduces IRS2/AKT2 and Ras/ERK1/2-dependent signaling, suggesting a causal link between decreased insulin signaling and accelerated atherosclerosis." (PMID 22347652, 2011). "To address the potential role of macrophage p38α in atherosclerosis, we placed groups of male and female p38MY-KO/ApoE−/− and their ApoE−/− littermates on HCD for 10 weeks, starting from 6–8 weeks of age." (PMID 21695272, 2011). "Our results clearly demonstrate that subchronic inhalation exposure to nano-NH can induce significant cardiovascular effects including exacerbation of atherosclerosis in ApoE−/− mice." (PMID 20864429, 2011). "The apoE KO mouse is a particularly useful model as it offers a unique opportunity to evaluate the mechanisms involved in the development of atherosclerosis and new therapies for treatment of this disease." (PMID 21896159, 2011). "The apolipoprotein E-knockout (apoE-KO) mouse is widely used as a model animal for atherosclerosis accompanied by spontaneous hypercholesterolemia, due to the reduced clearance of VLDL and LDL from the circulation." (PMID 21857965, 2011). "Another study showed that oral administration of BH4 slowed the progression of atherosclerosis in apoE-KO mice." (PMID 22190909, 2011).
atherosclerosis (continued). "Although the functions of macrophage ABCA1 and apoE in the development of atherosclerosis have been studied extensively, their potential combined role in atherosclerotic lesion development is still unexplored." (PMID 22022523, 2011). "The influence of the combination of EVO and seal oil on the development of atherosclerosis was analyzed in both female and male apoE-/- mice." (PMID 21371300, 2011). "In contrast, in aged apoE-/- mice (50-70-week-old) that exhibit both hypercholesterolemia and established atherosclerosis, an endothelial dysfunction, as demonstrated by a significantly blunted aorta relaxation response to ACh, has been observed." (PMID 22082357, 2011). "The effects of apoE in adipose tissue on body lipid homeostasis and atherosclerosis have been widely studied." (PMID 21772670, 2011). "The development of atherosclerosis was analyzed in double-knockout ApoE/L-sel (ApoE−/−L-sel−/−) mice and the corresponding ApoE−/− controls fed either a normal or a high cholesterol diet (HCD)." (PMID 21760899, 2011). "In 1992, two different groups simultaneously created the first gene-targeted murine model of atherosclerosis by disrupting the antiatherogenic apolipoprotein E (apoE) gene that is involved in cholesterol metabolism." (PMID 22082357, 2011). "In contrast, atherosclerosis-resistant BALB apoE-/- mice had much lower plasma glucose levels than B6.apoE-/- mice on either chow or Western diet and during an intraperitoneal glucose tolerance test." (PMID 22204493, 2011). "In an ApoE-/- murine model of atherosclerosis, early lesions were seen to be infiltrated by M2 (arginase I+) macrophages." (PMID 21526997, 2011). "Loss of apoE ultimately results in a mouse model of spontaneous atherosclerosis because apoE is important in the removal of circulating lipoproteins." (PMID 22582036, 2011). "In mice, deficiency for the Irs2 gene produces MetS, and partial or total inactivation of Irs2 aggravates atheroma development in the apolipoprotein E-null (apoE−/−) mouse model of atherosclerosis." (PMID 22347652, 2011). "Altogether, the data reveal a strongly impaired heart function and signs of heart failure in aged ApoE-/- mice with advanced atherosclerosis." (PMID 21711241, 2011). "It has been recently demonstrated that down-regulation of MMP-9 via insulin treatment will result in reduction of intimal lesions in atherosclerosis-prone diabetic apoE (-/-) mice." (PMID 22114787, 2011). "ApoE−/− mice with macrophage or endothelial cell-specific p38α deficiency were fed a high cholesterol diet (HCD) for 10 weeks and atherosclerosis development was assessed by histological and molecular methods." (PMID 21695272, 2011). "The apoE-knockout (apoE-/-) mouse is a well-established genetic mouse model of atherogenic hypercholesterolemia, in which mice spontaneously develop atherosclerosis with similar features to those observed in human type III familial hyperlipoproteinemia." (PMID 21241519, 2011). "We also demonstrated that elevated plasma levels of FFA in ApoE-/- mice can accelerate atherosclerosis, which confirmed the atherogenic action of FFA in vivo." (PMID 21486455, 2011). "The circulating monocytes of ApoE-/- mice with advanced atherosclerosis have increased TLR2 and TLR4 expression." (PMID 21526997, 2011). "Apolipoprotein E (apoE) is a major protein of the lipoprotein transport system that plays important roles in lipid homeostasis and protection from atherosclerosis." (PMID 22069485, 2011). "Our results show for the first time that exercise without dietary intervention did not favorably benefit atherogenic lipids (TC, LDL) or plaque accumulation on the aortic arch in ApoE knockout mice with advanced atherosclerosis." (PMID 21359188, 2011).
atherosclerosis (continued). "In apoE-/- mice suffering from hypercholesterolemia and atherosclerosis, statin therapy prevents the deficit in the bioavailability of NO in carotid arteries." (PMID 22082357, 2011). "To determine the effects of inhaled nano-NH on development of atherosclerosis in ApoE−/− mice, we quantified plaque formation on the ascending aorta." (PMID 20864429, 2011). "We previously established the apoE-/- and Faslpr/lpr (Fas-/-) double knockout B6 mouse as a model of accelerated atherosclerosis in lupus." (PMID 20482780, 2010). "This is further validated by SIRT1 activation or calorie restriction in ApoE-/- mice leads to protection against atherosclerosis progression by upregulating eNOS." (PMID 20663150, 2010). "To investigate if total PGC-1α deficiency affects atherosclerosis, we compared ApoE−/− PGC-1α−/− and ApoE−/− PGC-1α+/+ mice kept on a high cholesterol diet." (PMID 21042583, 2010). "In future work, the contribution of CS-exposure to the development of atherosclerosis in Ptx3/ApoE double KO mice has to be elucidated." (PMID 20920344, 2010). "In the ApoE knockout mice model of atherosclerosis we have recently found that atorvastatin increased Smad3 phosphorylation and ECM-related proteins, including CTGF, PAI-1 and type I collagen in the fibrous cap." (PMID 21152444, 2010). "The apoE-/-/LDL-/- double knockout mice are bearing considerable structural homology to human atherosclerosis." (PMID 20727187, 2010). "The effects on progression of atherosclerosis were assessed in aged apoE-/- mice (48-49 weeks) in which a substantial amount of plaques had developed." (PMID 21054825, 2010). "Treatment with L-4F, in the absence or presence of pravastatin, effectively reduced manifestations of lupus-like autoantibody production, glomerulonephritis, and osteopenia in our apoE-/-Fas-/- B6 murine model of accelerated atherosclerosis in SLE." (PMID 20482780, 2010). "Another recent study has investigated the programming of atherosclerosis by fetal malnutrition in ApoE*3 Leiden mouse." (PMID 20844591, 2010). "The firm evidence for the role ofeNOS in anti-atherogenesis stems from early experimental studies demonstratingaccelerated atherosclerosis in ApoE-/-/eNOS-/-double knockout mice compared to ApoE-/- mice." (PMID 20606250, 2010). "Our study revealed that UFP, analogous to Ox-LDL and Ox-PL, also induced similar pro-inflammatory responses, suggesting a possible mechanism for the in vivo observation that UFP exposure promoted atherosclerosis in ApoE-null mice." (PMID 20307321, 2010). "The role of JNK in atherosclerotic plaque formation in vivo was also examined using atherosclerosis-prone apolipoprotein E knockout mice (ApoE (−/−) mice)." (PMID 20182627, 2010). "The reduced expression of IL-18 in epididymal WAT is of special interest, since ApoE−/− IL-18−/− mice develop less atherosclerosis than control ApoE−/− mice." (PMID 21042583, 2010). "Expression of adipsin and other components of the alternative complement pathway correlate with atherosclerosis, suggesting that the elevation of adipsin in ApoE−/− PGC-1α−/− provides a pro-atherogenic contribution." (PMID 21042583, 2010). "Chronic exposure to ultrafine particles (UFP; Dp <100 nm) is reported to promote atherosclerosis in ApoE knockout mice." (PMID 20307321, 2010). "A20 gene transfer to the aortic arch of diabetic ApoE null mice that develop accelerated atherosclerosis, attenuated vascular expression of RAGE and phospho-PKCβII, significantly reducing atherosclerosis." (PMID 21151899, 2010).
atherosclerosis (continued). "In these ApoE−/− mice, the deletion of CCR5 protects from diet-induced atherosclerosis, associated with a more stable plaque phenotype, reduced mononuclear cell infiltration, Th1-type immune responses, and increased interleukin-10 expression." (PMID 21188276, 2010). "Apolipoprotein E (ApoE) knockout (KO) mice spontaneously develop atherosclerotic lesions and are widely used to study atherosclerosis." (PMID 20111605, 2010). "In apoE-/-Fas-/- B6 mice that develop accelerated atherosclerosis and autoimmunity, we used a dose of Apo-A1 mimetic peptide twice as much as previously used in apoE-/- B6 mice." (PMID 20482780, 2010). "For example, ApoE null mice have lower serum apolipoprotein E and develop significant early atherosclerosis but overexpression of catalase, an important antioxidative defense, appears to confer protection against early atherosclerosis." (PMID 21490698, 2010). "A number of studies show that airway exposure to concentrated ambient particles and single wall carbon nanotubes promotes the progression of atherosclerosis in apoE-/- mice." (PMID 21054825, 2010). "L-4F in the presence or absence of pravastatin reduced IgG anti-dsDNA, IgG anti-oxPLs, and IgG anti-cardiolipin antibody production and symptoms of glomerulonephritis and osteopenia in our apoE-/-Fas-/- B6 murine lupus model of accelerated atherosclerosis." (PMID 20482780, 2010). "To recapitulate this clinical observation, we determined plasma apoDexpression in normal and atherogenic mice with genetic depletion of apolipoproteinE (apoE), a commonly used rodent model of atherosclerosis." (PMID 19946382, 2009). "In order to verify that PARP-1 gene deletion protects against plaque formation in a murine model of atherosclerosis, aortas were collected from ApoE−/− or DKO mice after a 16-week regimen with regular (RD) or high-fat (HF) diet." (PMID 19823587, 2009). "The purpose of this study was to investigate the effect of systemic exposure to pristine C60 fullerenes by i.p. injection on the vascular function in apoE-/- mice with varying degree of atherosclerosis." (PMID 19243580, 2009). "Aside from atherosclerosis, ApoE-/- mice suffer from other conditions, such as increased oxidative stress and inflammation." (PMID 19416523, 2009). "To assess a causal role of NPY in atherosclerosis, we applied the NPY1-receptor–antagonist BIBP-3226 adventitially to endothelium-denuded carotid arteries of apolipoprotein E-deficient mice; treatment reduced atherosclerotic neointimal area by 50% (p = 0.03)." (PMID 19119412, 2009). "ApoE knockout mice display a marked increase in total plasma cholesterollevels and develop atherosclerosis with the deposition of fatty streaks in theproximal aorta at 3 months of age." (PMID 19946382, 2009). "Because of the increased plasma lipids in Paigen diet fed PDZK1/apoE dKO compared to apoE KO mice, we next evaluated atherosclerosis in the aortic roots and coronary arteries of these mice." (PMID 19956623, 2009). "In one condition (ApoE-/- mice sacrificed at 10 months of age), Mclk1+/- females had increased atherosclerosis (6.8 vs. 10 percent of aortic surface area, p = 0.0146)." (PMID 19416523, 2009). "PDZK1/apoE dKO mice fed with a high fat/high cholesterol diet (Western diet) develop increased aortic root atherosclerosis compared to apoE single KO mice, but fail to develop occlusive coronary artery disease and myocardial infarction." (PMID 19956623, 2009). "Ezetimibe, a novel lipid-lowering agent, selectively inhibits intestinal cholesterol absorption, reducing total cholesterol and TG levels and also reducing the development of atherosclerosis in apoE knockout mice." (PMID 19821987, 2009).